MLLT6 (MLLT6, PHD finger containing)
Description:
Involved in the stimulation of renal sodium reabsorption mediated by the epithelial sodium channel (ENaC) (By similarity). Upregulates ENaC expression in renal collecting duct cells by promoting DOT1L export from the nucleus to the cytoplasm, thus limiting DOT1L-mediated H3K79 methylation and transcriptional repression at the SCNN1A promoter.
Synonyms: AF17; FLJ23480
Tractability: PROTAC: ubiquitination databases record sites on it.
Gene: Protein-coding gene on chromosome 17 (38,705,273 to 38,729,795, forward strand). Ensembl gene ENSG00000275023.
Subcellular location: Nucleus; Cytoplasm
Subcellular location (Human Protein Atlas): Nucleoplasm
Gene Ontology:
Molecular function: histone binding; nucleosome binding; protein binding; histone reader activity
Biological process: positive regulation of gene expression; positive regulation of protein export from nucleus; regulation of DNA-templated transcription; chromatin organization
Cellular component: cytoplasm; nucleus
Genetic constraint (gnomAD): Loss-of-function variants: 19 observed, 85.2 expected, observed/expected ratio (o/e) 0.22, 90% interval 0.16 to 0.33. The upper end of that interval is the gene's LOEUF score, 0.33, which puts it in group 1 of 6, group 1 being the genes least tolerant of losing a copy. Missense variants: 1,186 observed, 1,337.6 expected, observed/expected ratio (o/e) 0.89, 90% interval 0.84 to 0.93. Synonymous variants: 598 observed, 593.85 expected, observed/expected ratio (o/e) 1.01, 90% interval 0.94 to 1.08.
Homologues: Orthologues: chimpanzee MLLT6 (99% identical), macaque MLLT6 (99% identical), dog MLLT6 (97% identical), pig MLLT6 (97% identical), rat Mllt6 (94% identical), mouse Mllt6 (93% identical), guinea pig MLLT6 (90% identical), rabbit MLLT6 (88% identical), tropical clawed frog mllt6 (50% identical), Caenorhabditis elegans phf-15 (9% identical). Paralogues in human: MLLT10 (43% identical), BRPF3 (17% identical), BRPF1 (16% identical), BRD1 (16% identical), JADE1 (12% identical), JADE2 (12% identical), PHF14 (12% identical), JADE3 (11% identical).
Diseases named in the same sentence as MLLT6 in open-access papers:
MLLT6 is named in the same sentence as 5 diseases in open-access papers, as found by Europe PMC text mining. Sharing a sentence is not in itself a finding about the gene and the disease. The quoted sentences say what the papers report.
cancer (5 papers, 2005 to 2024). A tumor composed of atypical neoplastic, often pleomorphic cells that invade other tissues. "However, there are three cancer-related genes (GRB2, GAS6, MLLT6) found in regions of gain at least five times more frequently than lost that are not kinases." (PMID 16457699, 2005).
MLLT6 also shares sentences with these, for which no sentence is quoted: tumor (2 papers); acute myeloid leukemia (1); leukemia (1); subarachnoid haemorrhage (1).